MRPL58 (mitochondrial ribosomal protein L58)
Description:
Essential peptidyl-tRNA hydrolase component of the mitochondrial large ribosomal subunit. Acts as a codon-independent translation release factor that has lost all stop codon specificity and directs the termination of translation in mitochondrion, possibly in case of abortive elongation. Involved in the hydrolysis of peptidyl-tRNAs that have been prematurely terminated and thus in the recycling of stalled mitochondrial ribosomes.
Synonyms: MRP-L58; DS-1; DS1; ICT1; mL62
Tractability: Small molecule: a structure with a bound ligand is known. Antibody: its Gene Ontology location is reachable by antibodies, with high confidence. PROTAC: ubiquitination databases record sites on it.
Gene: Protein-coding gene on chromosome 17 (75,012,664 to 75,021,266, forward strand). Ensembl gene ENSG00000167862.
Subcellular location: Mitochondrion
Subcellular location (Human Protein Atlas): Mitochondria; Nucleoplasm; Plasma membrane
Pathways (Reactome):
Metabolism of proteins: Mitochondrial ribosome-associated quality control; Mitochondrial translation elongation; Mitochondrial translation initiation; Mitochondrial translation termination
Gene Ontology:
Molecular function: peptidyl-tRNA hydrolase activity; translation release factor activity, codon nonspecific; translation release factor activity
Biological process: mitochondrial translational termination; mitochondrial translation; translational termination
Cellular component: mitochondrial large ribosomal subunit; mitochondrion; mitochondrial inner membrane; mitochondrial matrix
Genetic constraint (gnomAD): Loss-of-function variants: 15 observed, 22.63 expected, observed/expected ratio (o/e) 0.66, 90% interval 0.44 to 1.02. The upper end of that interval is the gene's LOEUF score, 1.02, which puts it in group 4 of 6, group 1 being the genes least tolerant of losing a copy. Missense variants: 235 observed, 252.68 expected, observed/expected ratio (o/e) 0.93, 90% interval 0.83 to 1.04. Synonymous variants: 93 observed, 94.4 expected, observed/expected ratio (o/e) 0.99, 90% interval 0.83 to 1.17.
Homologues: Orthologues: chimpanzee MRPL58 (99% identical), dog MRPL58 (84% identical), pig MRPL58 (81% identical), rabbit MRPL58 (81% identical), rat Mrpl58 (80% identical), mouse Mrpl58 (80% identical), guinea pig MRPL58 (79% identical), tropical clawed frog mrpl58 (53% identical), Drosophila melanogaster CG6094 (37% identical). Paralogues in human: MTRF1L (26% identical), MTRF1 (19% identical).
Diseases named in the same sentence as MRPL58 in open-access papers:
MRPL58 is named in the same sentence as 25 diseases in open-access papers, as found by Europe PMC text mining. Sharing a sentence is not in itself a finding about the gene and the disease. The quoted sentences say what the papers report.
metastatic tumors (1 paper, 2025). "It has been found that MRPL58 protein content was especially elevated in larger, late-metastatic tumors." (PMID 40452409, 2025).
tumor (7 papers, 2015 to 2025). "The mitochondrial metabolic pathway regulates mitochondrial ribosomal protein synthesis through MRPL4, MRPL58, and TSFM, enhances mitochondrial oxidative phosphorylation capacity, and provides continuous energy for tumor cells." (PMID 40989695, 2025).
MRPL58 also shares sentences with these, for which no sentence is quoted: cancer (9 papers); infection (9); breast carcinoma (3); hepatocellular carcinoma (3); osteosarcoma (3); colorectal cancer (2); gastric cancer (2); HIV-1 infection (2); lymphoma (2); abdominal aortic aneurysm (1); aneurysm (1); bacterial infection (1); Behçet's Disease (1); colon carcinoma (1); COVID-19 (1); iron deficiency (1); leukemia (1); lung carcinoma (1); mitochondrial disease (1); non-small cell lung carcinoma (1); pancreatic cancer (1); pneumonitis (1); small vessel stroke (1).